GSK3B (glycogen synthase kinase 3 beta)
Diseases named in the same sentence as GSK3B in open-access papers (continued):
Sharing a sentence is not in itself a finding about the gene and the disease.
breast cancer (continued). "Downregulation of GSK3β or USP10 resensitizes PI3Ki-resistant breast cancer models and patient-derived organoids to PI3K inhibition and induces tumor regression." (PMID 40991650, 2025). "Kenpaullone inhibits KLF4 by suppressing CDK1/cyclin B and GSK-3β, reducing proliferation and migration of breast cancer cells in canine mammary cancer and inducing cancer cell death, although its effects in humans require further investigation." (PMID 39995670, 2025). "There is evidence that GSK3β can act as an oncogene as well as a tumor suppressor in breast cancer, although it is predominantly considered to be a tumor suppressor." (PMID 41465855, 2025). "It enhances cell proliferation through the PI3K/AKT/GSK3β pathway, contributing to breast cancer (BC) metastasis." (PMID 40647480, 2025). "This indicated that LOC610012 inhibits the activity of canine mammary tumor cells through the PTGS2/EP3&GSK-3β axis." (PMID 40643495, 2025). "Overall, hERG activators inhibited the migration and invasion of breast cancer cells by suppressing the AKT/GSK3β signaling pathway and preventing the nuclear translocation of β-catenin." (PMID 39917621, 2025). "In various studies related to non-alcoholic steatohepatitis, resistance to Adriamycin in breast cancer, and ischemic injury, Gsk3b and Aqp4 have been identified as direct target genes of miR-29a-3p." (PMID 40529227, 2025). "Taken together, enhanced stemness property and activated ESR1/SGK3/GSK3β/β-catenin pathway was discovered in the alpelisib-resistant breast cancer cells." (PMID 40303291, 2025). "Our data showed that both SDUY429 and SDUY436 reduced the expression of pAKTS473, implying their anti-migratory and anti-invasive efficacy against breast cancer by downregulating the AKT/GSK3β/β-catenin axis." (PMID 39917621, 2025). "All synthesized compounds were evaluated for GSK‐3β inhibition effect to proliferation/survival on breast cancer cells MDA‐MB‐231 and MCF‐7." (PMID 39313991, 2024). "It has been shown that activated GSK-3β inhibits Cyclin D1 expression in tumor cells, including breast cancer and tongue squamous carcinoma." (PMID 39241034, 2024). "Silencing glycogen synthase kinase-3β (GSK-3β) with low expression in breast cancer can upregulate nuclear factor erythroid 2-related factor 2 (Nrf2) and GPX4 expression, inhibit tumor cell ferroptosis, and promote progression." (PMID 39664391, 2024). "Recent studies have found that the PI3K/AKT/GSK-3β pathway can modulate choline metabolism in breast cancer patients by regulating the expression of glycerophosphodiesterase EDI3 (GPCPD1)." (PMID 39769140, 2024). "bacciferum's ethanolic extract have been demonstrated in MCF-7 cells by modulation of apoptosis signalling molecules like Wnt2, GSK3β, and β-catenin in human breast cancer cells." (PMID 38800305, 2024). "H. bacciferum plant extract significantly inhibited the growth of breast cancer cells by modulating GSK3β, Wnt2, and β-catenin signaling, indicating that H." (PMID 38800305, 2024). "The MyD88 inhibitor TJ-M2010 interferes with the MyD88/PI3K/GSK-3β axis, consequently restraining breast cancer cell proliferation." (PMID 38347830, 2024). "Proteins activated as a result of HER2 signalling, including GSK3β and mTOR, are currently being evaluated in breast cancer with mixed outcomes." (PMID 36670508, 2023). "This action has been attributed to its ability to impede the AKT/GSK-3β pathway, evidenced by reductions in p-AKT, p-GSK-3β, and β-catenin levels, leading to suppression of breast cancer cell proliferation, migration, invasion, and induction of apoptosis." (PMID 38027882, 2023). "In breast cancer cells, CRB3b overexpression led to upregulation of GSK3-β and downregulation of β-catenin." (PMID 37737843, 2023). "Precisely, ZNF259 activates ERK/GSK3β by activating the ERK/GSK3β/Snail signaling pathway to promote breast cancer cell invasion and migration." (PMID 37396042, 2023).
breast cancer (continued). "Exposure of DATS in breast cancer cells has enhanced c-Myc and GSK-3β expression levels while downregulated the expression levels of phospho-glycogen synthase kinase-3β (p-GSK-3β), and ß-catenin." (PMID 37021043, 2023). "In this regard, previous studies have reported suppression of LPS-induced migration and invasion of breast cancer cells after targeting MyD88-dependent signaling pathways, for instance, MyD88/GSK-3β/Snail and MyD88/NF-κB/Snail." (PMID 37749630, 2023). "By downregulating the protein expression of p-Akt, p-GSK3B, and β-catenin, ACP blocked the Akt/GSK-3β signaling pathway in breast cancer cells, which in turn had anti-proliferation, anti-migration, and anti-invasion effects." (PMID 38102686, 2023). "Among these, four genes (APC, GSK3B, GSNK2B, GSNK2A2) are negative regulators of WNT signalling with deletions that are associated with metastasis in breast cancer patients after NAC exposure." (PMID 37345102, 2023). "A previous study revealed that cannabinoid receptors promote the chronic intermittent hypoxia-induced breast cancer metastasis via IGF-1R/AKT/GSK-3β." (PMID 36983855, 2023). "For example, it downregulates ERK1/2 through PPARγ in MCF-7 breast cancer cells, and inhibits the Akt/GSK-3β survival pathway by activating PTEN in SKBR3 and T47D breast cancer cell lines." (PMID 37511450, 2023). "Glycogen synthase kinase-3β (GSK-3β) knockdown attenuated the apoptotic effect of rapamycin and paclitaxel on breast cancer cells." (PMID 36671478, 2023). "Inhibition of GSK-3β leads to a decreased survival of breast cancer cells and attenuates their sensitivity to chemotherapy." (PMID 38139172, 2023). "The GSK-3β inhibitor 9-ING-41 potentiates the antitumor effects of conventional chemotherapeutic drugs against breast cancer cells." (PMID 36755314, 2023). "As a direct downstream target of AKT, GSK3β acts as a tumor suppressor in breast cancer, mediating the expression of cyclin D1 to regulate the cell cycle and increase chemosensitivity." (PMID 36900408, 2023). "For instance, GSK-3β expression is lowered in breast cancer tissues, while GSK-3β overexpression strengthens the inhibitory impact of Erastin on tumor growth." (PMID 37129745, 2023). "The elevated p-GSK3β expression level of the GPD1 overexpression group indicated that GPD1 inhibited glycogen synthesis in breast cancer cells." (PMID 37483742, 2023). "Notch3 was found to inhibit EMT by directly binding to the GSK3β promoter and transactivating GSK3β in breast cancer." (PMID 36139447, 2022). "For example, a study indicated that G3BP1 has an interaction with GSK-3β, contributing to promote breast cancer proliferation in vitro." (PMID 34967276, 2022). "High expression of Notch3 (p = 4.1 × 10−7) and GSK3β (p = 3.8 × 10−5) mRNAs correlated with an improved RFS for all patients with breast cancer." (PMID 36139447, 2022). "In a prognostic analysis, high expression of mRNA of both Notch3 and GSK3β was related to better RFS in all patients with breast cancer studied, which implies that Notch3 and GSK3β are beneficial biomarkers in this disease." (PMID 36139447, 2022). "TWS119 was found to promote the development of breast cancer in mice by regulating GSK‐3β protein expression." (PMID 35567291, 2022). "Direct or indirect interactions have been shown between these two signaling pathways; however, the relationship between Notch3 and GSK3β in EMT of breast cancer is still unclear." (PMID 36139447, 2022). "In breast cancer, the overexpression of a GSK-3β mutant acts as an inhibitor of endogenous wild-type GSK-3β protein, increases the sensitivity of breast cancer to chemotherapeutic compounds and blocks cell cycle progression." (PMID 34719320, 2022). "In conclusion, Notch3 and GSK3β mRNA overexpression suggest a good prognosis for patients with breast cancer." (PMID 36139447, 2022).
breast cancer (continued). "They concluded that blockade of the Wnt3a/FOXM1/β-catenin axis and activation of GSK-3β is essential for inducing apoptosis in breast cancer cells." (PMID 35744950, 2022). "We initially evaluated the effects of recombined Notch3 and GSK3β expression on breast cancer cell invasion using migration and invasion assays." (PMID 36139447, 2022). "Previously it has been shown that GSK3β signaling plays an important role in opioid-mediated apoptosis in breast cancer cells." (PMID 35568869, 2022). "ILK phosphorylates GSK3β at Ser9 in breast cancer, affecting the activation of the transcription factor AP1 and the stabilization of β-catenin, which is indirectly related to deregulation of proliferation, migration, and differentiation." (PMID 35379935, 2022). "We first performed an extensive analysis of the Breast Cancer Gene-Expression Miner v4.7 database to explore the relationship between Notch 3 and GSK3β." (PMID 36139447, 2022). "From data obtained from clinical tissue, Notch3 expression was significantly consistent with GSK3β expression in breast cancer tissue samples." (PMID 36139447, 2022). "Estrogen increases Nrf2 activity in MCF7 breast cancer cells through activation of the PI3K/GSK3β pathway." (PMID 36289931, 2022). "We analyzed the protein levels of Notch3 and GSK3β in the pathological parameters of 68 human breast cancer samples." (PMID 36139447, 2022). "Recent studies have shown that overexpression of GSK3β promotes erastin-induced ferroptosis and increases the sensitivity of breast cancer cells to chemotherapeutic agents." (PMID 35350242, 2022). "Decreased expression of GSK-3β was observed in the cancer tissues of breast cancer patients, and Nrf2 was highly expressed in low-GSK-3β-expressed breast cancer tissues." (PMID 36289931, 2022). "In this study, we revealed that Notch3 was an essential antagonist of EMT in breast cancer cells by transcriptionally upregulating GSK3β." (PMID 36139447, 2022). "The Hsp90 inhibitor, 17-AAG, rather than HDN-1, disrupted the interaction between Hsp90 and PGK1, and reduced GSK3β expression, resulting in significantly reduced inhibition of β-catenin expression, to maintain the stemness of breast cancer stem cells." (PMID 34403222, 2021). "Diallyl trisulfide, a garlic oil-soluble sulfur ingredient, has been reported to inhibit breast cancer stem cells via inhibition of GSK-3β-mediated Wnt/β-catenin pathway." (PMID 33746192, 2021). "GSK3β has been shown to be expressed at lower levels in skin cancer tumours and knockdown of GSK3β in breast cancer mammary models results in activation of Wnt signalling and the formation of adenosquamous carcinomas." (PMID 34739494, 2021). "In this context, PAD4‐dependent citrullination and nuclear translocation of GSK‐3β resulting in the activation of TGF‐β signalling in human breast cancer cells have previously been demonstrated." (PMID 34523218, 2021). "PAD4 also negatively regulates tumour invasiveness in breast cancer in vitro and in vivo models via citrullination of glycogen synthase kinase-3β (GSK3β)." (PMID 33573274, 2021). "PPA1 promotes proliferation, migration, and invasion of breast cancer through the PI3K/AKT/GSK3β pathway." (PMID 34595179, 2021). "Compounds 178–180 were found to possess activity against breast cancer when tested against CDK2/GSK-3β." (PMID 34885716, 2021). "It has previously been reported that PAD4 inhibition in breast cancer cells results in diminished nuclear localization of GSK‐3β and consequently activated TGF‐β signalling." (PMID 34523218, 2021). "In the present study three series of oxindole-benzofuran hybrids were designed and synthesised as dual CDK2/GSK-3β inhibitors targeting breast cancer (5a-g, 7a-h, and 13a-b)." (PMID 33327806, 2021). "Transgelin 2 directly interacts with PTEN to decrease PTEN expression and promotes paclitaxel resistance as well as the biological behaviours of breast cancer through regulating PI3K/AKT/GSK‐3β pathway." (PMID 34427967, 2021).
breast cancer (continued). "We further demonstrated that the SHP-1–induced suppression of EGFR inactivated the Ras/Erk/GSK3β pathway, thus enhancing understanding of the molecular mechanism of breast cancer progression, given that this pathway is known to be dysregulated in many cancers." (PMID 34591414, 2021). "The abilities of GSK-3β to influence the drug-sensitivity of pancreatic cancer cells and breast cancer cells are the subjects of this manuscript." (PMID 33917370, 2021). "Akt signalling inhibits glycogen synthase kinase-3β (GSK-3β) to promote glucose uptake and aerobic glycolysis in mammary tumour cells." (PMID 33592336, 2021). "In this study, we demonstrated that CCR2-CCL16 binding activates the GSK3β/β-catenin signaling pathway in order to maintain breast cancer CSC-like identity." (PMID 33500726, 2021). "GSK3β KD counteracted the stabilization of SIRT7 induced by ERK2 silencing in MDA-231 breast cancer cells and A549 lung cancer cells." (PMID 34433808, 2021). "Glycogen synthase kinase-3β (GSK3β) has been recognized as a suppressor of Wnt/β-catenin signaling, which is critical for the stemness maintenance of breast cancer stem cells." (PMID 34403222, 2021). "Most importantly, we revealed the underlying mechanism that PPA1 regulated breast cancer progression and EMT through the PI3K/AKT/GSK3β pathway." (PMID 34595179, 2021). "In summary, our results verify that PPA1 can act as an activator of PI3K/AKT/GSK3β/Slug-mediated breast cancer progression and that it is a potential therapeutic target for the inhibition of tumor progression." (PMID 34595179, 2021). "Studies using Rab3D knockdown or overexpression in breast cancer cells strongly suggest that this Rab-GTPase regulates EMT via the activation of the Akt/GSK-3β/Snail pathway." (PMID 34906074, 2021). "For example, in the MCF-7 breast cancer cell line, inhibition of GSK-3β increases autophagy by negatively modulating mTORC1." (PMID 33494241, 2021). "The previous study has shown that Wnt3a/GSK3β/Slug/Snail axis controlled EMT programs while coordinately regulating BRCA1 expression in breast cancer." (PMID 33589588, 2021). "PTEN loss occurs in both lung and breast cancers, leading to their progression via the activation of PI3K/Akt signaling, and downstream targets including EMT, GSK-3b, HIF-1a, and so on." (PMID 33670518, 2021). "In breast cancer, GSK3B knockdown has been shown to inhibit cell proliferation, and GSK3B overexpression has been shown to correlate with poor prognosis in TNBC patients." (PMID 35096583, 2021). "A recent report demonstrated that morin hydrate can effectively inhibit 12-O-tetradecanoylphorbol-13-acetate (TPA)-induced cancer cells metastatic through an Akt/GSK-3β/c-Fos signaling pathway in human MCF-7 breast cancer cells." (PMID 33092442, 2020). "ACTN4 knockdown decreases the activation of Akt and GSK-3β, and it reduces cell motility in breast cancer." (PMID 33363146, 2020). "Inhibition of GSK3β decreased the proliferation of rapamycin-sensitive breast cancer cells in an S6K1-dependent manner." (PMID 33081032, 2020). "Specific genes, such as PTEN, protein kinase A (PKA), GSK3B, CREBBP, SPEN have been linked to CSC biology and metastasis in breast cancer." (PMID 33167919, 2020). "Other studies have also demonstrated the pro-invasive nature of GSK3β in colorectal, pancreatic and breast cancer cells via the modulation of cytoskeletal microstructures and cytokine-mediated extracellular matrix degradation." (PMID 32503133, 2020). "To determine which signaling pathway confers phosphorylation of GSK3β in our cell model, we treated breast cancer cells with different concentrations of the ERK inhibitor PD98059." (PMID 32944401, 2020). "In the present study, we demonstrated that SHP2 functions as a key modulator of the proliferation of breast cancer cells by promoting the G1-to-S phase transition through regulating Cyclin D1 stability via the PI3K/AKT/GSK3β signaling pathway." (PMID 32944401, 2020).
breast cancer (continued). "Morin hydrate, a flavonoid isolated from Morus alba L., inhibited metastatic potential of 12-O-tetradecanoylphorbol-13-acetate (TPA)-treated MCF-7 breast cancer cells via the inhibition of MMPs, uPA, uPAR, and the Akt/GSK-3β/c-Fos pathway." (PMID 32521759, 2020). "Another previous study showed that GSK3β increased protein synthesis, thereby enhancing cell proliferation in breast cancer through regulation of the eukaryotic translation initiation factor 4E (eIF4E)-binding protein 1 (4E-BP1)." (PMID 32503133, 2020). "Next, the effects of LY294002, a PI3K/AKT inhibitor, were further examined on GSK3β (Ser9) phosphorylation and Cyclin D1 expression in the 2 breast cancer cell lines." (PMID 32944401, 2020). "All of these, with the exception of TCP1, have also been linked to breast cancer, while FLNA, GSK3B and CCT2 are specifically linked to TNBC." (PMID 32127582, 2020). "In summary, we have identified an association of SIRT2 with enhanced CD8+ TEM cell differentiation in breast cancer, an event mediated at least in part by activated aerobic oxidation as well as the inhibition of GSK3β acetylation in CD8+ T cells." (PMID 33061819, 2020). "It is well known that AKT regulates breast cancer metastasis by inhibiting GSK-3β activity and subsequently leading to Snail stabilization." (PMID 31913260, 2020). "We and others have previously shown that inhibition of GSK3β in human colon and breast cancer cells induced mitotic catastrophe by disturbing centrosome dynamics and the assembly of spindle apparatus, with the cells ultimately undergoing apoptosis." (PMID 32678196, 2020). "We observed that GSK3β is upregulated in breast cancers versus normal mammary cells and that higher expression of GSK3β correlates with worse overall survival in TNBC patients." (PMID 30845991, 2019). "Using clinicaldata, we further evaluated and confirmed the overall prognosticdependency of breast cancer patients on GSK-3β." (PMID 31354196, 2019). "Publicly available datasets also were analyzed to examine if the expression of GSK3β correlates with the overall survival of breast cancer patients." (PMID 30845991, 2019). "TCGA RPPA data was mined to compare the expression of GSK3β in TNBCs and other types of breast cancer." (PMID 30845991, 2019). "In this study we report the contribution and prognostic significance of GSK3B to two breast cancer subtypes;ductal carcinoma in-situ (DCIS) and invasive ductal carcinoma (IDC) using the Oncomine platform." (PMID 31354196, 2019). "Evidence from work on MCF7 breast cancer cells suggests that the growth inhibitory effect of GSK3β inhibition results subsequent decrease in cyclin D1 expression." (PMID 30446846, 2019). "That study demonstrated that Src regulates cell cycle protein expression through protein kinase B/glycogen synthase kinase 3 beta and extracellular signal-regulated kinase 1/2 pathways in the human breast cancer cell line MCF-7." (PMID 30634502, 2019). "In our study, western blot analyses of MDA-MB-231 and HCC1806 breast cancer cells CSCs showed that Gomisin M2 downregulates the Wnt/β-catenin self-renewal pathway and cyclin D1 expression via GSK3β activation." (PMID 31612865, 2019). "Collectively, our results showed that lncRNA‐ZEB2‐AS1/PI3K/Akt/GSK3β/Zeb2 axis facilitates tumor progression and is a potential prevention target in breast cancer." (PMID 30825262, 2019). "We identified GSK3β as one such target that is highly upregulated in breast cancer patients, and this upregulation correlates with poor prognosis." (PMID 30845991, 2019). "GSK3-β expression was shown increased in multiple cancers including breast cancer and it correlates with poor prognosis in breast cancer patients." (PMID 31362447, 2019). "Taken together, these results indicated that upregulated IQUB promoted breast cancer cell proliferation and migration via activating Akt/GSK3β/β‐catenin signaling pathway, which played an important part in the tumorigenesis and development of breast cancer." (PMID 29968965, 2018).